MIR504 (microRNA 504)
Synonyms: hsa-mir-504; MIRN504; mir-504
Gene: MicroRNA gene on chromosome X (138,667,711 to 138,667,793, reverse strand). Ensembl gene ENSG00000207800.
Gene Ontology:
Biological process: miRNA-mediated post-transcriptional gene silencing
Cellular component: RISC complex
Homologues: Orthologues: chimpanzee ptr-mir-504 (100% identical), macaque mml-mir-504 (99% identical), dog MIR504 (98% identical), pig ssc-mir-504 (93% identical), guinea pig MIR504 (92% identical), mouse Mir504 (90% identical), rabbit MIR504 (67% identical).